LEP (leptin)
Diseases named in the same sentence as LEP in open-access papers (continued):
Sharing a sentence is not in itself a finding about the gene and the disease.
Hepatic steatosis (continued). "As this inhibition of triglyceride transport is rescued in leptin-deficient mice, regulating VLDL metabolism by hepatic VLDLR, LPL, and leptin may represent a new therapeutic strategy for preventing diet-induced liver steatosis." (PMID 31815184, 2019). "First, the hepatic steatosis in SHROB rats only partially mimics the hepatic consequences of human MetS in light of the dissimilarities in the biology of leptin in rodents and man, where unequivocal involvement of leptin receptor in hepatic steatosis has yet to be demonstrated." (PMID 30201044, 2018). "Moreover, constitutive activation of Nrf2 induced by Keap1 gene knockdown promoted high fat diet (HFD)-induced fatty liver and glucose intolerance in Leptin-null (Lepob/ob) mice." (PMID 29241092, 2018). "In obese patients, reduced adiponectin and increased leptin levels may result in hepatic steatosis and the activation of inflammation and fibrogenesis." (PMID 28643267, 2018). "Leptin has been reported to protect against hepatic steatosis, increasing β-catenin levels which might contribute to leptin regulation of SREBP-1c expression in hepatic stellate cells (HSCs)." (PMID 28218651, 2017). "Probably, mSJH acts through leptin signaling pathway to combat FFAs-induced hepatic steatosis." (PMID 28358008, 2017). "However, it is clear that APS markedly reduced HFSTZ-altered body weight, fasting serum insulin level, MOMA-IR, serum leptin level, hepatic TG and hepatic steatosis." (PMID 29258283, 2017). "Regarding the post-therapy leptin levels, the univariate analyses showed an association with sex, post-therapy BMI, HOMA-IR, C3 levels, and hepatic steatosis, whereas the multivariate analyses showed that sex, post-therapy BMI, and C3 levels were associated factors." (PMID 27870883, 2016). "Here we show that an SGLT2 inhibitor ipragliflozin improves hepatic steatosis in high-fat diet-induced and leptin-deficient (ob/ob) obese mice irrespective of body weight reduction." (PMID 26977813, 2016). "We suggest that the fructose-induced hepatic steatosis mice exhibited a leptin resistance." (PMID 27941940, 2016). "In this study, we show that ipragliflozin improved hepatic steatosis in diet-induced and genetically leptin-deficient (ob/ob) obese mice irrespective of body weight reduction." (PMID 26977813, 2016). "Fasting plasma glucose, lipids/lipoproteins, insulin and leptin levels were quantified, histopathologic score of hepatic steatosis and inflammation were assessed, and the responses of common checkpoints of insulin and leptin signalling responsible for lipogenesis and gluconeogenesis were analyzed." (PMID 25658428, 2015). "The aim of the current study is to determine the temporal relationships between the development of hepatic steatosis and the onset of insulin and leptin resistance in hypothalamus and liver in male Wistar rats (six weeks of age) fed chow or HFHS diet for up to 8 weeks." (PMID 25658428, 2015). "Hence, we are ongoing research on the other factors that affect the weight lose by KBH-1 treatment, such as hepatic steatosis in liver and leptin resistance in hypothalamus." (PMID 26649747, 2015). "Melatonin can reverse the methylation of leptin and decreased liver steatosis." (PMID 24822223, 2014). "Leptin may contribute toenhance hepatic steatosis by changing actions of insulin on tissues and its receptors, and it may influence the development of NASH through the regulation of inflammatory responses." (PMID 24829591, 2014). "In particular the ob/ob model is based on a genetic leptin deficiency that drives hyperphagia, but that underlying etiology is not considered a common cause in human hepatic steatosis pathophysiology." (PMID 24956382, 2014). "Moreover, in the leptin/leptin receptor mice models, hepatic steatosis was more severe in ob/ob mice than in db/db mice – consist with a somewhat milder phenotype when deleting the receptor versus its ligand." (PMID 23341960, 2013).
Hepatic steatosis (continued). "Indeed, normalization of plasma leptin level by administration of exogenous leptin stimulated fatty acid oxidation and attenuated alcoholic fatty liver in mice." (PMID 24155903, 2013). "The ob/ob mice develop hepatic steatosis but not hepatic inflammation or fibrosis, possibly due to the loss of normal leptin signalling." (PMID 22295101, 2012). "Dietary interventions preventing lipodystrophy or normalizing leptin and adiponectin levels prevents or ameliorates hepatic steatosis in mice, suggesting that adipose tissue responsiveness to trans-10, cis-12 CLA could be the main contributing factor." (PMID 21869929, 2012). "This PTP1B inhibitory property may represent a promising role for curcumin to treat fructose-induced hepatic steatosis induced by hepatic insulin and leptin resistance." (PMID 22991573, 2012). "Evidence has demonstrated that the level of haptoglobin was increased in obese mice, and since both leptin and haptoglobin were increased in the NC, this might presumably indicate overweight animals in this group, which also corresponds to the liver steatosis." (PMID 22007198, 2011). "Hepatic fat deposition was also reduced by exogenous GH levels, as was the expression of adipocyte-derived adipokines (adiponectin, leptin and resistin), which might improve lipid metabolism and hepatic steatosis." (PMID 20653983, 2010). "We believe that leptin therapy in these selected individuals may address these abnormalities and improving hepatic de novo lipogenesis with a readout of improved fasting hypertriglyceridemia and liver steatosis (potentially hepatocyte injury and inflammation)." (PMID 40520449, 2025). "In addition, elevated leptin levels in patients with fatty liver disease may impair gallbladder contractility, leading to cholestasis and stone formation." (PMID 41446861, 2025). "Hence, we designed a case–control study to evaluate the impact of three of the most common adipokines (Nrg4, leptin, and adiponectin) on alleviating hepatic steatosis during the early recovery phase following sleeve gastrectomy (SG, one of the most popular surgical methods)." (PMID 38632600, 2024). "Similarly, leptin administration improved or prevented hepatic steatosis development in ob/ob mice." (PMID 36834959, 2023). "Additionally, leptin promotes adipogenesis and the immune response and favors MetS Other examples include ghrelin and fetuin A which concurrently aggravate hepatic steatosis and prevent liver fibrosis." (PMID 35355551, 2022). "However, this association does not necessarily indicate a causal or pathogenic role for leptin in causing hepatic steatosis." (PMID 34943809, 2021). "Thus, physiological leptin levels are necessary to prevent hepatic steatosis." (PMID 33316927, 2020). "Besides these direct effects as a result of a deficiency of leptin action within the liver, any disturbance in the hypothalamic leptin signaling can have important consequences in glucose and lipid metabolism, and finally also to contribute to liver steatosis development." (PMID 33316927, 2020). "In nonobese HCV core transgenic mice, hepatic steatosis is associated with downregulated leptin gene and hypoadiponectinemia, and these effects may be ameliorated by adiponectin treatment." (PMID 33167521, 2020). "We hypothesized that the chronic programming effect of prenatal dexamethasone on liver steatosis involves leptin epigenetic modifications with liver inflammatory changes, wherein melatonin may play a protective role in the progression of chronic liver steatosis." (PMID 30424542, 2018). "Together, these data confirm that both lowered insulin and leptin sensitivity occurred during the development of hepatic steatosis upon HFHS dieting, and suggest that the impairment in hepatic PI3K/Akt pathway may occur earlier than that in hepatic STAT3/SOCS3 pathway." (PMID 25658428, 2015).
Hepatic steatosis (continued). "Furthermore, a serum leptin level of ≥8.6 ng/ml was independently associated with the presence of hepatic steatosis (≥5%) (OR, 6.195; 95% CI, 1.409–27.240; P = 0.016), but not hepatic fibrosis or inflammation." (PMID 24524410, 2014). "Interestingly, we have observed that a high HOMA-IR index is an insufficient condition to cause hepatic steatosis in absence of hepatic resistance to leptin." (PMID 24298268, 2013). "In addition, the reduction of serum leptin levels could also be related to increases in smaller adipocytes and reduced liver steatosis in HFD-fed mice supplemented with the bacterial strain due to the role of leptin in fat accumulation in peripheral tissues." (PMID 22844426, 2012). "Third, obesity disrupts adipokine balance (e.g., leptin and adiponectin), and OSA exacerbates this imbalance, promoting hepatic steatosis and fibrosis." (PMID 41334428, 2025). "MASLD prevalence was significantly higher with elevated leptin (44% vs. 30%, p < 0.001), while quantitative steatosis measures confirmed this relationship with higher CAP values (270 vs. 241 dB/m, p < 0.001) and fatty liver index scores." (PMID 40956476, 2025). "In conclusion, this study found that serum leptin levels are higher in NAFLD subjects compared to healthy controls, and it is a good independent predictor for the detection of liver steatosis." (PMID 38738048, 2024). "The nomenclature of MASLD emphasizes the central role of metabolic dysfunction in the pathogenesis of fatty liver, in which CRP affects the regulation of fat metabolism by leptin, forming the first hit." (PMID 37893085, 2023). "Hepatic steatosis and the resulting NAFLD can lead to additional chronic inflammation by secretion of inflammatory cytokines such as IL6, TNF-alpha, and leptin." (PMID 35407455, 2022). "Leptin also controls hepatic sympathetic nerve activity via activation of PI3K and AMPK signaling, which leads to improvement in the fatty liver disease." (PMID 33935782, 2021). "Numerous factors such as leptin, TNF-α, and IL-6 are involved in the initiation and progression of hepatic steatosis and related metabolic dysfunction." (PMID 32528465, 2020). "Leptin appears to exert a dual action in experimental NAFLD models; it protects against liver steatosis, at least in the early stages of the disease, but it also acts as an inflammatory and fibrogenic mediator when the disease persists or continues." (PMID 33324348, 2020). "Irrespective of the group of patients, SIRT1, adiponectin and leptin showed a substantially overlapping strength of prediction for EFT and liver steatosis." (PMID 33202604, 2020). "Thus, we speculate that this newly characterized regulatory pathway makes an important contribution to the amelioration of hepatic steatosis in subjects with lipodystrophy under leptin treatment, which until now has often been attributed solely to leptin induced anorexia and weight loss." (PMID 31222048, 2019). "Wang further found that the injection of recombinant murine FGF21 reduces IL-6, TNF-α, and leptin mRNA levels in WAT of monosodium glutamate-induced obese rats, with the improvement of glucose tolerance, lipid metabolic spectrum, and hepatic steatosis." (PMID 27616737, 2016). "The findings lead to introduction of an informative biomarker panel including INS, PPARA, LEP, SREBF1, and ALB proteins related to the fatty liver disease." (PMID 28224024, 2016). "Adipose tissue inflammation in the HF group was indicated by hepatic steatosis, pronounced macrophage infiltration and CLS formation, and elevations in plasma monocyte chemoattractant protein-1 (MCP-1), leptin and proinflammatory cytokine concentrations." (PMID 26132316, 2015). "SR4 also prevented hepatic steatosis in HFD mice, concomitant with decreased liver lipid triglycerides, increased leptin and decreased adiponectin levels, and normalization of liver enzymes ALT and AST." (PMID 24376752, 2013).
Hepatic steatosis (continued). "Similar correlations were found, regarding leptin and ghrelin levels, mitochondrial enzymes activities (complex I and III), IMCL accumulation, and degree of hepatic steatosis, inflammation and fibrosis." (PMID 22359625, 2012). "The role of some adipocytokines, such as leptin and TNF-α in hepatic steatosis has also been increasingly studied." (PMID 21961071, 2011). "Leptin has been proposed as a signaling molecule that reduces hepatic lipogenesis and cholesterol synthesis by inhibiting the expression of SREBP-1 and cholesterol-related genes, thereby reducing cholesterol levels and alleviating hepatic steatosis." (PMID 40098735, 2025). "Regular aerobic exercise such as brisk walking, Nordic walking, etc. has a beneficial effect on the remission of hepatic steatosis mainly due to the regulation of fatty acid oxidation (using adiponectin and AMP kinase), leptin, intrahepatic SREBP-1c levels and the action of antioxidant enzymes." (PMID 39857800, 2025). "Afteronly four doses, the disease phenotype, including morbid adiposity,hyperphagia, and hepatic steatosis, was completely reversed by bothPASylated leptin versions, but not by the non-PASylated leptin ifadministered at the same dose." (PMID 40335095, 2025). "The field has also witnessed the emergence of novel therapeutic strategies targeting the adipokine-hepatokine axis, with mechanistic studies elucidating the roles of key mediators like adiponectin, leptin, and FGF21 in hepatic steatosis, inflammation, and fibrosis." (PMID 40868109, 2025). "Leptin levels were undetectable, and abdominal ultrasonography confirmed mild hepatic steatosis without evidence of significant fibrosis." (PMID 40842493, 2025). "Leptin shows a dual role in the development of NAFLD, preventing hepatic steatosis in healthy individuals and early in the disease, but it may act as an inflammatory and fibrotic factor when the disease persists or progresses." (PMID 37893085, 2023). "These mice develop fatty liver without fibrosis when fed a normal chow diet, and their resistance to hepatic fibrosis—unlike db/db mice—can be attributed to the requirement of leptin for fibrosis development." (PMID 36555433, 2022). "The main mechanism accounting for the anti-steatotic effect of leptin action has not been clearly delineated, but some believe that leptin replacement improves hepatic steatosis merely by ameliorating hyperphagia." (PMID 31222048, 2019). "However, these HFD-induced elevations in hepatic steatosis (p<0.001), AUCs for GTT and ITT (p=0.032 & p=0.018, respectively), serum leptin (p=0.038) and TC (p=0.038) were significantly alleviated after 10 weeks of treadmill running." (PMID 30343561, 2018). "Although some have also reported that leptin resistance plays an important role in liver steatosis, this did not correlate with our findings of chronic liver steatosis programming." (PMID 30424542, 2018). "INS, PPARA, LEP, SREBF1, and ALB are the introduced biomarker panel for fatty liver disease." (PMID 28224024, 2016). "In this study, serum levels of leptin were associated with HOMA-IR and hepatic steatosis, but not hepatic fibrosis and inflammation." (PMID 24524410, 2014). "Therefore, the elevated leptin mRNA levels we observed in pgWAT, especially in our EtOH-fed OVX mice, may reflect compensatory mechanisms to suppress hepatic steatosis." (PMID 40381698, 2025). "Interestingly, AGPAT2 re-expression in the liver of total KO mice did not rescue the massive liver steatosis whereas leptin replacement did, as well as it improved glucose homeostasis." (PMID 35250856, 2022). "Serum concentration of leptin (20.64 ± 22.02 ng/ml versus 9.97 ± 11.97 ng/ml) and insulin (15.81 ± 17.73 μU/ml versus 8.80 ± 7.07 μU/ml) were significantly higher in patients with hepatic steatosis compared to those without hepatic steatosis (P < 0.001)." (PMID 32728230, 2020).
Hepatic steatosis (continued). "While a high-isoflavone soy protein isolate diet was found to protect obese Zucker rats from liver steatosis, supplementation with daidzein alone did not improve their liver steatosis scores or body weight, energy intake, and serum leptin and adiponectin levels." (PMID 32102233, 2020). "Notably, replacement therapy with recombinant leptin potently reverses hepatic steatosis, even though adipose tissue mass does not recover." (PMID 31222048, 2019). "Thus, prenatal dexamethasone induces liver steatosis at ~120 days via altered leptin expression and liver inflammation without leptin resistance." (PMID 30424542, 2018). "Similarly, models of fatty liver disease, e.g. induced by dietary fructose or by lack of leptin showed that occludin protein expression is decreased and portal endotoxin levels are elevated in the small intestine." (PMID 24321090, 2013). "However, under certain circumstances, such as diet-induced obese rats, leptin may not be capable of alleviating hepatic steatosis, probably due to leptin resistance." (PMID 33316927, 2020). "Moreover, the logarithmically transformed FGF-21 levels were positively and significantly correlated with liver steatosis grade (B = 0.516, P < 0.001) whereas logarithmically transformed adiponectin (B = −0.217, P = 0.067) and leptin levels (B = 0.003, P = 0.978) were not." (PMID 31750276, 2019). "However, over time the leptin levels, although still elevated above normal, are not able to maintain sufficient compensatory oxidation in non-adipose tissues with the generation of toxic lipid species that impact on the pathogenesis of liver steatosis." (PMID 30717085, 2019). "HFHFr males presented hypertriglyceridemia, but not hepatic steatosis, partially due to enhanced liver PPARα-related fatty acid β-oxidation and the VLDL-promoting effect of leptin." (PMID 37764693, 2023). "A clinical study demonstrated a positive correlation between circulating leptin and high-serum ALT or hepatic steatosis independent of BMI and body fat, although the significance of this finding is not clear." (PMID 33671547, 2021).